MET (MET proto-oncogene, receptor tyrosine kinase)
Diseases named in the same sentence as MET in open-access papers (continued):
Sharing a sentence is not in itself a finding about the gene and the disease.
myopia (3 papers, 2009 to 2024). "This study examined the genetic association of the MET gene with refractive error (low/moderate myopia, high myopia, and hypermetropia) as well as the quantitative measures of refraction, axial length, corneal curvature, and anterior chamber depth." (PMID 20011629, 2009). "This is supported by the fact that we and others have found the HGF gene, which codes for the primary ligand for MET, to be associated with both high and low/moderate myopia." (PMID 20011629, 2009). "The strong biological role of HGF in the development of myopia makes it not unreasonable to hypothesize that other genes in the HGF signaling cascade, such as MET, may also play a critical role in myopia." (PMID 20011629, 2009).
myxofibrosarcoma (3 papers, 2012 to 2018). A malignant fibroblastic neoplasm arising from the soft tissue. "Interestingly, overexpression of the oncogene MET in myxofibrosarcoma, as a frequent event, was strongly related to higher grades and seems to have a causative function in conferring an aggressive phenotype." (PMID 24289252, 2013). "The MET oncogene has also been shown to be influential in myxofibrosarcomas." (PMID 22736953, 2012). "Typically, myxofibrosarcoma gain and/or amplification was mapped to 7p21.3-q31.1, q31.1-q31.33, q33-q36.2, p21.3, p21.2, p14.1-q11.23, q31.33-q33, p21.2-p14.1, q11.23-q21.3, q36.2-q36.3, which, respectively are known to harbour tumour-associated genes, including TIF, BRAF, MLL3, SMO, and MET." (PMID 24289252, 2013).
neurofibroma (3 papers, 2013 to 2024). An intraneural or extraneural neoplasm arising from nerve tissues and neural sheaths. "Previously, our genomic analysis of human MPNST progression revealed that MET and HGF copy number gains are present at the earliest stage of neurofibroma transformation and increase during metastasis and resistance." (PMID 32245042, 2020).
oligodendroglioma (3 papers, 2021 to 2025). A well-differentiated (WHO grade II), diffusely infiltrating neuroglial tumor, typically located in the cerebral hemispheres. "MET amplification was found in one case of ganglioglioma, while two cases carried amplifications of MYCN, including a case of IDH-mutant and 1p/19q co-deleted oligodendroglioma and a case of IDH-wild-type diffuse astrocytic tumor." (PMID 41517303, 2025). "Not only did they reassess the percentage of c-MET-positive cells present in different GBM types, but they also found that oligodendrogliomas, a previously c-MET-negative cancer, also expressed a substantial level of the marker." (PMID 34055785, 2021).
ovarian clear cell cancer (3 papers, 2016 to 2024). An invasive malignant neoplasm that arises from the ovary and is characterized by a predominance of clear and hobnail malignant epithelial cells. "Inhibition of MET significantly decreased the proliferation of ovarian clear cell carcinoma (OCCC) cell line RMG1 and increased apoptosis." (PMID 38030594, 2024). "Treatment with crizotinib decreased cell proliferation and triggered apoptosis in ovarian clear cell carcinomas that expressed elevated c-MET levels." (PMID 31766284, 2019). "Amongst 16 normal ovarian, 47 serous carcinoma and 16 ovarian clear cell carcinoma tissues examined, high levels of c-MET were significantly detected in clear cell carcinomas." (PMID 31766284, 2019). "In this study, we investigated the therapeutic effects of c-MET inhibition in ovarian clear cell carcinoma (OCCC)." (PMID 27917934, 2016).
Pleural effusion (3 papers, 2015 to 2020). The presence of an excessive amount of fluid in the pleural cavity. "In order to evaluate heterogeneity among NSCLC tumors, we quantitated the expression and phosphorylation levels of common RTKs, such as the HER family, MET and IGF-1R, in tumor cells isolated from pleural effusion and/or fine needle aspirations (FNAs)." (PMID 26439803, 2015).
primary effusion lymphoma (3 papers, 2017 to 2021). A large B-cell lymphoma located in the body cavities, characterized by pleural, peritoneal, and pericardial fluid lymphomatous effusions and that is always associated with human herpes virus-8 (HHV-8). "The HGF/c-MET pathway appears further largely activated in malignant cells from primary effusion lymphoma (PEL): here the expression of plexin B1 is required for c-MET-mediated survival of PEL cells." (PMID 30642077, 2019).
Sarcomatoid carcinomas of the lung (3 papers, 2017 to 2025).
scleroderma (3 papers, 2012 to 2017). Scleroderma is a rare autoimmune connective tissue disorder characterized by abnormal hardening of the skin and, sometimes, other organs. "HGF treatment of scleroderma lung fibroblasts as well as HGF treatment of TGFβ-treated normal lung fibroblasts transfected with wild type MET is associated with decreased collagen, connective tissue growth factor (CTGF, CCN2) and smooth muscle α-actin (SMA)." (PMID 27584154, 2016). "To confirm that cleavage and loss of the MET C-terminus can occur with the endogenous MET, we used non-transfected scleroderma LF, A549, and ATII cell lines." (PMID 27584154, 2016).
thyroid nodule (3 papers, 2013 to 2024). A small circumscribed mass in the THYROID GLAND that can be of neoplastic growth or non-neoplastic abnormality. "Immunohistochemical analysis of thyroid nodules has shown that Gal-3 and c-MET expressions are significantly higher in malignant lesions compared to benign ones." (PMID 39664377, 2024).
Ureteral obstruction (3 papers, 2019 to 2020). Obstruction of the flow of urine through the ureter. "HGF can bind to MET, which is a transmembrane receptor of the tyrosine kinase superfamily, and its inhibitory effects on tissue fibrosis have been confirmed in various research models, such as residual kidney, unilateral ureteral obstruction, and diabetic nephropathy." (PMID 31781634, 2019).
Vestibular schwannoma (3 papers, 2013 to 2020). A vestibular schwannoma (also known as acoustic neuroma, acoustic neurinoma, or acoustic neurilemoma) is a benign, usually slow-growing tumor that develops from the VIIIth cranial nerve supplying the inner ear. "As previous studies implicated signaling downstream of MET as a potential therapeutic target in vestibular schwannoma, we assessed the consequences of inhibiting MET in NF2-null Schwann cells." (PMID 27363027, 2016).
acral melanoma (2 papers, 2020 to 2021). "For example, in a case of acral melanoma with KIT mutation, targeting MET with a selective inhibitor successfully overcame resistance to KIT inhibition, as confirmed also in cell line studies." (PMID 32659961, 2020). "Moreover, in c-KIT-mutant acral melanoma, the addition of TKIs targeting MET and KIT showed increased efficacy compared to KIT alone in the presence of hepatocyte growth factor, the ligand for MET." (PMID 33807778, 2021).
adenosquamous carcinoma (2 papers, 2023). A carcinoma composed of malignant glandular cells and malignant squamous cells. "Notably, the MET exon 14 skipping mutation possessed a higher frequency in pleomorphic carcinoma and adenosquamous carcinoma than in adenocarcinoma." (PMID 37400762, 2023).
alcoholic liver diseases (2 papers, 2016 to 2025). A disorder caused by damage to the liver parenchyma due to alcohol consumption. "To assess the therapeutic efficacy of the recombinant Tarim red deer HGF/SF Receptor (MET) agonist produced via this method, we established a mouse model of alcoholic liver disease characterized by chronic alcohol feeding followed by acute alcohol gavage, referred to as the NIAAA or Gao-Binge model." (PMID 40723349, 2025).
angiosarcoma (2 papers, 2015 to 2025). A malignant tumor arising from the endothelial cells of the blood vessels. "Moreover, highly aggressive angiosarcomas exhibit considerable genomic plasticity, allowing them to activate alternative signaling pathways (e.g., MET, AXL, and MAS), thereby bypassing VEGFR inhibition by sunitinib." (PMID 41341391, 2025). "MET overexpression was found in 17% of angiosarcomas and 14% of UPS." (PMID 25844809, 2015). "Our preliminary data on HGF expression, however, are promising since we could demonstrate a statistically significant correlation between HGF and MET overexpression namely in angiosarcomas and undifferentiated pleomorphic sarcomas." (PMID 25844809, 2015). "We demonstrate that a subset of angiosarcomas and undifferentiated pleomorphic sarcomas (UPS) harbor MET amplifications, MET copy number gains or show MET/HGF overexpression." (PMID 25844809, 2015). "Interestingly, we could demonstrate that MET as well as HGF overexpression occurs in both post-radiation and primary angiosarcomas." (PMID 25844809, 2015).
bile duct cancer (2 papers, 2018 to 2023). "In a 3-D culture of bile duct cancer cells in collagen gel, HGF induced robust activation of MET, ERK, and AKT, which was associated with enhanced expression of genes involved in bile duct development and subsequent branching of tubulogenesis." (PMID 30322054, 2018).
bladder tumors (2 papers, 2010 to 2011). "Hypomethylation of a specific LINE-1 promoter was also found to induce an alternate transcript of the MET oncogene in bladder tumors and across the entire urothelium of tumor-bearing bladders." (PMID 20421991, 2010). "Since bladder tumors display both hypomethylation of L1s and overexpression of MET, our next step was to determine whether hypomethylation of the specific L1 promoters and their associated alternate transcripts, including L1-MET, were present in uncultured bladder tumors." (PMID 20421991, 2010). "Hypomethylation of specific LINE-1 promoters can alter the transcriptome, including activating an alternate transcript of the MET oncogene, not only in primary bladder tumors but also in premalignant urothelium across entire bladders with tumors." (PMID 20421991, 2010). "Specifically, hypomethylation of a L1 promoter induces an alternate transcript of the MET oncogene in bladder tumors and across the entire urothelium of tumor-bearing bladders." (PMID 20421991, 2010). "In addition to L1s being hypomethylated and transcriptionally active in bladder tumors we also found that a specific L1 located within the MET oncogene is active across entire bladders with cancer." (PMID 20421991, 2010).
bone sarcoma (2 papers, 2023 to 2024). A sarcoma that arises from the bone. "In contrast, in bone sarcomas, the amplification of MET and MYC was significantly associated with prognosis, and the prognosis of patients with amplification of these two genes was significantly worse than that of patients without amplification." (PMID 37546405, 2023).
carcinomas of tongue (2 papers, 2021 to 2025). "Red rectangles represent the hit genes involved in the treatment of tongue cancer (TERT, Bcl-2, CDK4/6, CDK2, VEGF, ER, RXR,c-KIT, MET, FGFR, PPAR8, PFFP, MMPs, CDK4, AR, F2, IGFR)." (PMID 39863836, 2025). "Moreover, FOXM1 can bind directly to the promoter of MET, which establishes, together with AKT, a positive feedback loop relevant not only to NSCLC but also to carcinomas of tongue and pancreas." (PMID 33660397, 2021).
carcinosarcoma (2 papers, 2019 to 2021). A malignant tumor composed of a mixture of carcinomatous and sarcomatous elements. "The newly identified MET exon 14 skipping mutation from a rare carcinosarcoma case urges extending screening scope for MET exon 14 skipping mutations and further evaluation in clinical trials would be an important step for the success of MET target therapy in clinical practice." (PMID 31369639, 2019). "PHA-665752 treatment and targeting of MET significantly reduced cell viability in a dose-dependent and metaplastic carcinosarcoma-specific manner." (PMID 34508101, 2021). "To inhibit the PI3K pathway, we used multiple approaches and found that cell viability of primary Trim24COE metaplastic carcinosarcoma cells was reduced in a dose-dependent manner by inhibiting either c-MET, with Critzotinib and PHA-665752, or PI3K/mTOR, with dual inhibitor Dactolisib." (PMID 34508101, 2021).
childhood cancer (2 papers, 2022). "There are currently multiple ongoing or recruiting trials of anti-c-MET agents including pediatric patients, hence it is expected that additional key data will become available regarding the safety and efficacy of these agents for childhood cancers in the near future." (PMID 36034555, 2022). "Personalized medicine in childhood cancer aims for the identification of actionable alterations and some promising molecular drug targets are already being translated into clinical applications (e.g., ALK, NTRK, MET, BRAF)." (PMID 35159116, 2022).
choriocarcinoma (2 papers, 2018 to 2025). An aggressive malignant tumor arising from trophoblastic cells. "Notably, we found the highest c-MET immunoreactivity in the epithelial elements of the various components of TGCTs: teratoma, yolk sac tumor and choriocarcinoma." (PMID 30159127, 2018).
depression (2 papers, 2019 to 2023). "GWAS for the HGA/GR ratio identified two genetic loci that mapped to the TAC1 and ASNS genes, which are known to be involved in depression and neurotransmission, while the ratio MET/TYR identified the gene AGBL1 previously linked to neurodegeneration in mice." (PMID 31273200, 2019). "The authors also supported the theory of altered HGF/c-MET signaling in depression with the finding that both MET and HGF mRNA expressions were decreased in brain samples of adult depressed individuals." (PMID 34590201, 2023).
diffuse astrocytoma (2 papers, 2023). A low-grade (WHO grade II) astrocytic neoplasm. "These include diffuse astrocytoma, MYB- or MYBL1-altered; diffuse low-grade glioma, MAPK pathway-altered; polymorphous low-grade neuroepithelial tumor of the young (BRAF mutations and FGFR2 fusions); and infant-type hemispheric glioma (alterations in NTRK, ROS1, ALK, or MET)." (PMID 37509316, 2023).
diffuse intrinsic pontine glioma (2 papers, 2021 to 2022). A neuroglial tumor that arises from the middle portion of the brain stem. "In diffuse intrinsic pontine glioma (DIPG—also called diffuse midline gliomas), H3K27M mutations, as well as ACVR1, FGFR1, MET, and PIK3CA mutations, were clonal." (PMID 33673104, 2021).
esophageal tumors (2 papers, 2015 to 2017). "Treatment with AMG 337, a selective c-Met kinase inhibitor, led to a partial or near complete response in eight (62%) of 13 patients with MET-amplified gastroesophageal junction, gastric, or esophageal tumors." (PMID 29108334, 2017). "In addition, crizotinib, which is a small molecule inhibitor of c-MET—approved for the treatment of ALK-positive NSCLC by the FDA, has been shown to be effective in the treatment of a subset of patients with c-MET-amplified gastric or esophageal tumors." (PMID 25593196, 2015).
familial cancer (2 papers, 2021). "One mutation passes our criteria for the Hereditary Cancer panel, corresponding to the variant located in chr7:116771936 (rs56391007) producing C → T; c.3029C>T; p.Thr1010Ile, located in the MET gene, identified for Father as well." (PMID 33763108, 2021). "The second variant is located in the MET gene, part or our Hereditary Cancer panel, on chr7:116771936 (rs56391007) and produces C → T; c.3029C>T; p.Thr1010Ile." (PMID 33763108, 2021). "In contrast to numerous inactivating mutations in tumor suppressor genes, activating mutations contributing to familial cancer are rare and include the genes RET, MET, KIT, and ALK." (PMID 33916261, 2021).
ganglioglioma (2 papers, 2025). A well differentiated, slow growing neuroepithelial neoplasm composed of neoplastic, mature ganglion cells and neoplastic glial cells. "For example, KCND2 has been linked to the regulation of ERK signaling in ganglioglioma, with recurrent copy number breakpoints within KCND2 associated with MET amplification." (PMID 39140252, 2025).
gliosarcoma (2 papers, 2020 to 2022). A rare histological variant of glioblastoma (WHO grade IV) characterized by a biphasic tissue pattern with alternating areas displaying glial and mesenchymal differentiation (WHO). "Transcriptomic analysis showed MET upregulation in the initial gliosarcoma and in the lung metastasis." (PMID 32014051, 2020). "MET overexpression was detected in the initial gliosarcoma and lung metastasis, possibly contributing to invasiveness." (PMID 32014051, 2020). "MET overexpression in the primary gliosarcoma and the lung metastasis may be responsible for the fibroblast-like morphology of these tumors and possibly, the metastatic potential, as c-MET is a receptor tyrosine kinase involved in epithelial to mesenchymal transition, invasion and metastasis." (PMID 32014051, 2020).
hepatitis C (2 papers, 2011 to 2022). "qPCR analysis of liver biopsyspecimens demonstrated that these unannotated transcripts, as well as IRF1,TRIM22 and MET, were also upregulated in hepatitis C with mild inflammation andno fibrosis." (PMID 21359205, 2011).
Hodgkin disease (2 papers, 2016 to 2019). "HGF and c-MET clearly contribute to MM pathogenesis, while data reported from various authors about a potential relationship between prognosis and c-MET expression in Hodgkin lymphomas are instead sometimes discordant." (PMID 30642077, 2019).
human papillomavirus infection (2 papers, 2023 to 2024). "These GS genes were mainly enriched in receptor tyrosine kinase signaling, MET signaling, human papillomavirus infection, PDGF signaling, the VEGFA–VEGFR2 signaling pathway, and the EGF–EGFR signaling pathway." (PMID 39766034, 2024).
inflammatory myofibroblastic tumor (2 papers, 2011 to 2024). A multinodular intermediate fibroblastic neoplasm that arises from soft tissue or viscera, in children and young adults. "LRRFIP1 has been implicated in 8p11 myeloproliferative syndrome through its fusion with FGFR1, in inflammatory myofibroblastic tumors with ALK and in atypical Spitz tumors with MET." (PMID 38338888, 2024).
insulinoma (2 papers, 2018 to 2020). "Indeed, Meg3 and c-MET levels are described to be inversely correlated, both in MEN1-associated PanNENs and sporadic insulinomas." (PMID 32537434, 2020).
invasive carcinoma (2 papers, 2015). A carcinoma that is not confined to the epithelium, and has spread to the surrounding stroma. "Strong (+++) and very strong (++++) MET expression we observed for samples described as HSIL and invasive carcinoma." (PMID 25888626, 2015).
ischemia (2 papers, 2016 to 2022). A hypoperfusion of the BLOOD through an organ or tissue caused by a PATHOLOGIC CONSTRICTION or obstruction of its BLOOD VESSELS, or an absence of BLOOD CIRCULATION. "In normal tissues, a trend towards decreased phosphorylation of c-MET in response to ischemia was detected, reaching statistical significance after 20 min (N20) of ischemia." (PMID 26742633, 2016). "In normal tissue, significant change in the overall phosphorylation of c-MET was detected following 20 min (N20) of ischemia, which was also present in the analysis of individual isoforms." (PMID 26742633, 2016). "It is unclear whether patients with high baseline levels of c-MET phosphorylation respond to ischemia differently than patients with no c-MET phosphorylation at baseline." (PMID 26742633, 2016).
mucinous adenocarcinoma (2 papers, 2017 to 2021). An invasive adenocarcinoma composed of malignant glandular cells which contain intracytoplasmic mucin. "We found that 3.0 and 4.0% of the 594 CRC patients (63.6% of COAD, 26.1% of READ and 10.3% of mucinous adenocarcinoma (MUAD)) in the dataset respectively harbored genetically altered EGFR and c-MET." (PMID 34512327, 2021).